PCK1 (phosphoenolpyruvate carboxykinase 1)
Diseases named in the same sentence as PCK1 in open-access papers (continued):
Sharing a sentence is not in itself a finding about the gene and the disease.
lung carcinoma (7 papers, 2020 to 2024). "Shao and colleagues reported that PCK1 promoted the activation of nuclear SCAP-sterol regulatory element-binding protein 1 (SREBP1) in lung cancer cells, thereby contributing to cancer growth." (PMID 38670942, 2024). "Our study thus sheds light on the oncogenic role of PCK1 in lung cancer and its enzymatic function in modulating glucose metabolism." (PMID 37407566, 2023). "The metabolic effects of MLK4 knockdown in lung cancer are therefore consistent with a reduction in PCK1 activity in cancer cells." (PMID 37407566, 2023). "Surprisingly, PCK1 promotes lipid synthesis through the same mechanism as HCC in lung cancer." (PMID 39578429, 2024). "Here, we showed that PCK1 exerts oncogenic function in lung cancer." (PMID 37407566, 2023). "Notably, PCK1 protein expression is high in lung cancer cell lines, and its knockdown also mediated prominent inhibitory effects in cancer cell growth, invasion and colony formation." (PMID 37407566, 2023). "Moreover, we showed that MLK4 and PCK1 are oncogenic factors in lung cancer with potential clinical and prognostic significance." (PMID 37407566, 2023). "Recent research findings have documented elevated expression levels of PCK1 (or PCK2) in various cancers, such as colon cancer, pancreatic cancer, lung cancer, melanoma, lymphoma, and metastatic breast cancer cells." (PMID 38670942, 2024). "Involvement of highly significant DEGs including SLCO1A2, OLFM4, RTKN2, CYP1A1, and MUC5AC plays a key role in rheumatoid arthritis development.Highly significant DEGs including OLFM4, RTKN2, CYP1A1, MUC5AC, CYP2A6, PCK1, and PITX1 have been reported to encourage the development of lung cancer." (PMID 38137330, 2023). "Here, we analyzed the expression of GLUT1, the prime glucose transporter, and of PCK1 and PCK2, the cytoplasmic and mitochondrial isoforms of PEPCK, in 450 samples of non‐small cell lung cancer (NSCLC) and in 54 NSCLC metastases using tissue microarrays and whole tumor sections." (PMID 32777161, 2020). "The lack of PCK1 or PCK2 expression in some NSCLCs leads to the question, how lung cancer cells remain viable and maintain anabolic biosynthesis in these tumors, if blood perfusion drops." (PMID 32777161, 2020).
pancreatic cancer (7 papers, 2012 to 2024). "We next studied the possible underlying signaling mechanisms of PCK1-driven pancreatic cancer cell growth." (PMID 34620839, 2021). "The underlying signaling mechanisms of PCK1-driven pancreatic cancer growth may warrant further characterizations." (PMID 34620839, 2021). "The research of our group shows that PCK1 is overexpressed in pancreatic cancer and that PCK1 silencing significantly inhibits cancer cell proliferation, migration, and invasion and induces cell apoptosis." (PMID 39578429, 2024). "Further research found that ectopic overexpression of PCK1 mediated Akt activation to promote pancreatic cancer proliferation and metastasis." (PMID 39578429, 2024). "To confirm the bioinformatics results, we examined PCK1 expression in local pancreatic cancer tissues." (PMID 34620839, 2021). "Since the status of KRAS have been studied in pure IPMN and NEN in multiple studies, we further searched COSMIC database for the information of the other two mutated genes (PCK1 and MLL3) in pancreatic neoplasms." (PMID 34801052, 2021). "In pancreatic cancer cells, Akt-mTOR activation was largely inhibited by PCK1 shRNA, but was augmented after ectopic PCK1 overexpression." (PMID 34620839, 2021). "When combining the blotting data of all five sets of human tissues, we found that PCK1 protein and phosphorylation in pancreatic cancer tissues were significantly elevated (P < 0.05 vs. “N” tissues)." (PMID 34620839, 2021). "PCK1 protein and phosphorylation were significantly elevated as well in the established and primary human pancreatic cancer cells." (PMID 34620839, 2021). "The pathological mechanisms of increased PCK1 expression and phosphorylation in pancreatic cancer require further investigations as well." (PMID 34620839, 2021). "Western blotting assays were performed to test PCK1 protein expression and results confirmed PCK1 protein upregulation in pancreatic cancer tissues (“Patient #1/#2/#4”, three representative patients)." (PMID 34620839, 2021). "In the primary pancreatic cancer cells derived from three patients, pPC1/pPC2/pPC3, the application of the lentiviral PCK1 shRNA (Seq1) led to robust PCK1 mRNA silencing." (PMID 34620839, 2021). "The qRT-PCR assay results found that PCK1 mRNA levels in pancreatic cancer tissues (“T”) were again significantly higher than those in adjacent normal tissues (“N”)." (PMID 34620839, 2021). "In the primary pancreatic cancer cells, pPC1/ pPC2/pPC3, stable transfection of the OE-PCK1 construct led to robust PCK1 mRNA upregulation." (PMID 34620839, 2021). "We show that PCK1 mRNA and protein levels are significantly elevated in human pancreatic cancer tissues and cells." (PMID 34620839, 2021). "As shown PCK1 mRNA levels in pancreatic cancer tissues (“T”, n = 178) were significantly higher than those in normal pancreatic tissues (“N”, n = 4)." (PMID 34620839, 2021). "In established and primary pancreatic cancer cells, PCK1 silencing (by shRNA) or CRISPR/Cas9-induced PCK1 knockout potently inhibited cell growth, proliferation, migration and invasion, and induced robust apoptosis activation." (PMID 34620839, 2021). "In pancreatic cancer cells, shRNA-induced PCK1 silencing or CRISPR/Cas9-induced PCK1 KO robustly inhibited cell growth, viability, proliferation, migration and invasion, and provoked apoptosis activation." (PMID 34620839, 2021). "RNA-seq analyzing of differentially expressed genes (DEGs) in PCK1-silenced pancreatic cancer cells implied that DEGs were enriched in the PI3K-Akt-mTOR cascade." (PMID 34620839, 2021). "IHC staining assay results further confirmed PCK1 protein upregulation in pancreatic cancer tissues in Patient #1/#2/#4." (PMID 34620839, 2021). "Conversely, ectopic overexpression of PCK1 in pancreatic cancer cells accelerated cell proliferation and migration." (PMID 34620839, 2021). "Conversely, ectopic overexpression of PCK1 in established and primary pancreatic cancer cells augmented cell proliferation and mobility." (PMID 34620839, 2021).
pancreatic cancer (continued). "The comparison revealed that ALDOB, SLC2A2, PC and PCK1 mRNA levels were significantly higher in the liver metastatic lesions in comparison to the primary pancreatic tumors." (PMID 22412968, 2012). "PCK1 is a potential therapeutic target for pancreatic cancer." (PMID 34620839, 2021). "Here we found that PCK1 is important for Akt-mTOR activation in pancreatic cancer cells." (PMID 34620839, 2021). "Moreover, the PCK1-S90A suppressed Akt-mTOR activation and inhibited pancreatic cancer migration and proliferation." (PMID 34620839, 2021). "The current study tested the expression and potential functions of PCK1 in pancreatic cancer." (PMID 34620839, 2021). "PCK1 upregulation is also detected in established and primary human pancreatic cancer cells." (PMID 34620839, 2021). "In addition, the GTEx project analyzing the RNA-Seq data of human cancers demonstrated that PCK1 mRNA levels in pancreatic cancer tissues (“T”) were significantly higher than those in normal pancreatic tissues (“N”)." (PMID 34620839, 2021). "Collectively, PCK1 is a potential therapeutic target for pancreatic cancer." (PMID 34620839, 2021). "In this study, our results suggest that PCK1 could be an important gene for pancreatic cancer cell growth." (PMID 34620839, 2021). "Here we show that PCK1 is required for pancreatic cancer cell growth both in vitro and in vivo." (PMID 34620839, 2021). "We next studied whether PCK1 silencing could provoke apoptosis activation in pancreatic cancer cells." (PMID 34620839, 2021). "Therefore, we analyzed whether PCK1 silencing shall affect this cascade in pancreatic cancer cells." (PMID 34620839, 2021).
non-small cell lung carcinoma (5 papers, 2021 to 2024). A group of at least three distinct histological types of lung cancer, including non-small cell squamous cell carcinoma, adenocarcinoma, and large cell carcinoma. "In an earlier study, PCK1 mediated sterol regulatory element-binding protein 1(SREBP1) activation in esophageal cancer (ESCC) and non-small-cell lung cancer (NSCLC)." (PMID 36193307, 2022). "In non-small cell lung cancer (NSCLC), PCK1 can promote nuclear SREBP-1 activation by phosphorylating Insig1/2, which is associated with TNM stage and progression of NSCLC." (PMID 35912181, 2022).
steatosis (5 papers, 2018 to 2023). Increased lipid within the cytoplasm of cells. "Mechanistically, loss of PCK1 not only promotes steatosis by enhancing lipid deposition, but also induces fibrosis through HSC activation via paracrine secretion of PDGF-AA, thus promoting MAFLD progression." (PMID 36918564, 2023). "To further examine the function of PCK1 in steatosis in vitro, we overexpressed (PCK1-OE) using the AdEasy adenoviral vector system and knocked out PCK1 (PCK1-KO) using the CRISPR-Cas9 system in human hepatocytes." (PMID 36918564, 2023). "We found that PCK1 mRNA31 was induced in response to lipid accumulation after 14 days of steatosis induction (>15-fold increase, p < 0.01)." (PMID 30250238, 2018).
atherosclerosis (4 papers, 2021 to 2025). A disease characterized by the build-up of fatty material and calcium deposition in the arterial wall resulting in partial or complete occlusion of the arterial lumen. "This DM-specific association of s-PCK1-Ab is distinct from previous results that showed that most of the SEREX autoantibodies screened using sera from patients with atherosclerosis were associated with multiple atherosclerosis-related diseases such as AIS and CVD." (PMID 37904164, 2023). "PCK1 was screened by SEREX using sera from patients with atherosclerosis, so the antibody levels in other atherosclerosis-related diseases were also examined." (PMID 37904164, 2023). "Phosphoenolpyruvate carboxykinase 1 (PCK1) was recognized as an antigen by serum IgG antibodies in the sera of patients with atherosclerosis." (PMID 37904164, 2023). "We performed SEREX screening and identified PCK1 (Accession Number: NM_002591.4) as the antigen recognized by antibodies in the sera of patients with atherosclerosis." (PMID 37904164, 2023). "During our analysis, the initial SEREX screening identified PCK1 as an antigen as recognized by serum IgG in patients with atherosclerosis, and subsequently, recombinant GST-tagged PCK1 protein of 301 amino acids was purified." (PMID 37904164, 2023). "Overlap of the three protein coding genes (and protein names) with atherosclerosis in PubMed yielded 1 hit for Zbp1, 9 hits for Pck1, and 0 hits for Pmepa1." (PMID 35052410, 2021). "In this study, we identified phosphoenolpyruvate carboxykinase 1 (PCK1, also known as PEPCK) by SEREX screening using sera from patients with atherosclerosis and found that its autoantibody levels were specifically elevated in patients with DM." (PMID 37904164, 2023). "The direct role of Pck1 in atherosclerosis has not been studied." (PMID 35052410, 2021).
clear cell renal cell carcinoma (4 papers, 2020 to 2025). "A literature search revealed that PCK1 has been associated with diabetic nephropathy, acute kidney injury models, and renal clear cell carcinoma, and it is closely linked to proteinuria and extracellular matrix fibrosis in animal models." (PMID 40442892, 2025). "The results showed a correlation between the expression of PCK1 and G6PC and prognosis in patients with HCC and clear cell renal cell carcinoma (ccRCC)." (PMID 36092708, 2022).
Hyperinsulinemia (4 papers, 2011 to 2025). An increased concentration of insulin in the blood. "If the hyperinsulinemia resulted in the elevated mRNA levels of Srebp-1c, Fas and Scd1 in hepatocytes from ad libitum fatty rats, the question becomes why it did not cause elevation of Gck and reduction of Pck1 mRNA expression." (PMID 21731709, 2011). "Similarly, dexamethasone did not affect the mRNA levels of the gluconeogenic genes Pck1 and G6pc in our model probably due to hyperinsulinemia-induced repression of gluconeogenesis." (PMID 35052508, 2021).
Alzheimer disease (3 papers, 2010 to 2017). A progressive, neurodegenerative disease characterized by loss of function and death of nerve cells in several areas of the brain leading to loss of cognitive function such as memory and language. "(2010) observed associations of ZNF224 (rs3746319) and PCK1 (rs8192708) with impaired cognition, an intermediate phenotype of Alzheimer's disease." (PMID 29201552, 2017). "That same year, researchers used neuropathology and cognitive function proximate to death as the intermediate phenotypes for Alzheimer disease and identified two genes—ZNF224 and PCK1—involved in the development of Alzheimer disease." (PMID 23094028, 2012).
colitis (3 papers, 2022 to 2024). Inflammation of the colon. "Previous studies have also reported that exhibits a therapeutic effect in experimental colitis by inhibiting the CEBPB/PCK1 and CEBPB/EFNA1 pathways, which are associated with the PI3K-Akt and P38 MAPK pathways." (PMID 38675921, 2024). "Recently, nintedanib, one of the two FDA-approved IPF therapeutics, is shown to attenuate experimental colitis via inhibiting the PCK1 pathway." (PMID 38081956, 2023). "In vivo experiments, nintedanib significantly alleviated DSS-induced colitis in mice by inhibiting CEBPB/PCK1 and CEBPB/EFNA1 signaling pathways." (PMID 35910380, 2022). "In summary, this study shows that inhibition of super-enhancer–driven CEBPB/PCK1 and CEBPB/EFNA1 signaling pathways can reduce LPS-induced barrier dysfunction in vitro and improve DSS-induced experimental colitis in vivo." (PMID 35910380, 2022). "In conclusion, we found that PCK1 and EFNA1 are highly expressed in colitis and they are regulated by CEBPB through two super-enhancers, and we further demonstrate their role in vivo and in vitro." (PMID 35910380, 2022). "In LPS-induced Caco-2 cells, drugs commonly used in clinical colitis including tofacitinib, oxalazine, mesalazine, and sulfasalazine inhibited mRNA levels of CEBPB, PCK1, and EFNA1." (PMID 35910380, 2022). "To verify whether CEBPB regulates PCK1 and EFNA1 to improve colitis, we designed the interfering RNA of CEBPB." (PMID 35910380, 2022).
esophageal cancer (3 papers, 2021 to 2024). A primary or metastatic malignant neoplasm involving the esophagus. "PCK1 pS90 was upregulated in esophageal carcinoma, correlating with poor prognosis." (PMID 34620839, 2021). "Moreover, the levels of PCK1 pS90, Insig1 pS207/Insig2 pS151, and SREBP-1 are associated with the tumor, metastasis stage, and progression of esophageal squamous cell carcinoma, suggesting PCK1 activity-regulated SREBP-1 as a potential target for the diagnosis and treatment of esophageal cancer." (PMID 35912181, 2022). "Additionally, as an AKT-dependent protein kinase, PCK1 promotes SREBP1-dependent lipogenesis, which is positively correlated with esophageal cancer progression and metastasis." (PMID 39578429, 2024).
gastric cancer (3 papers, 2022 to 2024). A primary or metastatic malignant neoplasm involving the stomach. "In gastric cancer, increased PCK1 levels promote the TCA cycle, activate the RAS/extracellular signal-regulated kinase (ERK) signaling pathway, induce MMP-9 expression, and eventually lead to gastric cancer metastasis." (PMID 39578429, 2024).
Impaired glucose tolerance (3 papers, 2013 to 2023). An abnormal resistance to glucose, i.e., a reduction in the ability to maintain glucose levels in the blood stream within normal limits following oral or intravenous administration of glucose. "On the contrary, the low dose of PN-treated mice increased the gene expression of Pck-1, which might be due to the low dose of PN-treated mice having impaired glucose tolerance and developing an insulin-resistant state." (PMID 37426418, 2023). "Increased PCK1 gene expression increases basal hepatic glucose production (HGP), triggering impaired glucose tolerance." (PMID 23690974, 2013).
lipid metabolic disorders (3 papers, 2023 to 2025). "Interestingly, the members of PPAR signaling pathway, APOA1 and PCK1 were often enriched in biological processes involved in lipid metabolism together with APOA4, and were related to lipid metabolic disorders." (PMID 38665091, 2024).
liver fibrosis (3 papers, 2023 to 2024). "In addition, this study revealed that liver Pck1 deficiency aggravates liver fibrosis and inflammation." (PMID 39259165, 2024). "Hepatic gene expression analyses indicated that the expression of genes involved in inflammation and liver fibrosis was greatly attenuated by PCK1 restoration in L-KO mice." (PMID 36918564, 2023). "Thus, PCK1-mediated hepatic fibrosis may be involved in paracrine disorders." (PMID 36918564, 2023).
malaria (3 papers, 2017 to 2022). Malaria is a serious and sometimes fatal disease caused by a parasite that commonly infects a certain type of mosquito which feeds on humans. "Six genes (TGFB1, CD36, THBS1, FABP1, PCK1, and IRS1) were involved with malaria, PPAR signaling, and the adipocytokine signaling pathway." (PMID 36193307, 2022). "Among them, malaria, PPAR signaling, and the adipocytokine signaling pathway reached statistical significance (FDR value of <1 and p < 0.05) and included TGFB1, CD36, THBS1, FABP1, PCK1, and IRS1." (PMID 36193307, 2022).
nonalcoholic fatty liver disease (3 papers, 2023 to 2024). "Here the authors report that deficiency of Pck1 in the liver leads to nonalcoholic fatty liver disease via activation of the RhoA/PI3K/AKT pathway in a study with male mice." (PMID 36918564, 2023).
renal fibrosis (3 papers, 2021 to 2026). A final common manifestation of a wide variety of chronic kidney diseases characterized by glomerulosclerosis and tubulointerstitial fibrosis. "PCK1 overexpression inhibits renal fibrosis by protecting the mitochondrial ribosome." (PMID 41546098, 2026). "Compared with the detection of total RNA in mouse kidneys, the transcript level of Pck1 in fibroblast mRNA alone would be more meaningful when determining whether this can be used as a precise marker of renal fibrosis." (PMID 33777519, 2021). "Hnf4α, Pck1 and Timp-1 may play a pivotal role in the early activation of fibroblasts, providing novel therapeutic strategies for early prediction and treatment of renal fibrosis." (PMID 33777519, 2021).